LATS1 (large tumor suppressor kinase 1)
Diseases named in the same sentence as LATS1 in open-access papers (continued):
Sharing a sentence is not in itself a finding about the gene and the disease.
cancer (continued). "This suggests LATS1 may be involved in invasion and metastasis of cancer, a concept which would need to be confirmed by in vivo animal model." (PMID 22909338, 2012). "Interestingly, a search of the Oncomine database revealed only two studies where a difference in LATS1 expression was observed between normal and cancer samples." (PMID 19656388, 2009). "In humans, loss of expression of Lats1/2 (Wts homolog) and mutations in WW45/Sav and Mob (homolog of mats) have been found in several tumor cell lines, while YAP expression is frequently elevated in cancers." (PMID 18833298, 2008). "A YAP-related signaling pathway could be proposed as part of the inflammatory cascade to develop new anti-inflammatory or anti-viral drugs that affect the upstream kinase activity of YAP, including MST1/2 and LATS1/2, which would be beneficial for the treatment of cancer and inflammatory diseases." (PMID 37397250, 2023). "Dysregulation of the hippo pathway has been associated with cancer progression, including the abnormal expression and activity of yes-associated protein (YAP) and transcriptional co-activator with PDZ-binding motif (TAZ), and a deficiency in large tumor suppressor kinase 1/2 (LATS1/2) level." (PMID 35804016, 2022). "However, whether the mechanisms of LATS1/2 activation and YAP inhibition caused by forskolin can explain its potential anti-cancer effect remains to be examined." (PMID 33467099, 2021). "Although Hippo pathway activity is frequently suppressed, and the activity or expression of YAP and TAZ is elevated in cancer, it is important to note that the components of the central Hippo pathway cascade, including LATS1, LATS2, YAP, and TAZ, are not frequently mutated or deleted." (PMID 29673168, 2018). "However, even though human Lats1 can interact with human Cdc25B, it remains unclear whether Lats1 is involved in centrosome duplication during interphase in human normal and/or cancer cells." (PMID 26530630, 2015). "This, in turn, enhances the expression of transforming growth factor-β (TGF-β), activates epidermal growth factor receptor (EGFR), and inhibits LATS1 and LATS2, leading to cancer cell proliferation." (PMID 40699764, 2025). "We found that MST1, LATS1, and LATS2 were consistently expressed at low levels in the cytoplasm of basal cells of the normal epithelium, dysplastic cells of the OED, and cancer cells." (PMID 38444414, 2024). "In animal cells, the LATS1/2 kinases are central elements of the Hippo pathway, involved in tissue growth control, and NDR1/2 kinases have been involved in multiple forms of cancer." (PMID 39705284, 2024). "Several SPOP substrates important in a cancer context have been previously identified, such as BRD proteins, DRAK1 and LATS1." (PMID 37622993, 2023). "Consistent with our findings, a recent study showed that LATS1/2 KO inhibited ESR1 gene expression and ER+ cancer cell growth through YAP/TAZ40." (PMID 35654829, 2022). "Strikingly, every Lats1/2f/f; YAPf/f; TAZf/f; lsl-EYFP; K8CreERT2 mouse examined (n = 11) showed near-complete ablation of carcinoma development within the mammary ducts." (PMID 36443313, 2022). "The mutation and expression changes of its core components (MST1/2, LATS1/2, YAP, and TAZ) can promote the migration, invasion, and malignant progression of cancer cells." (PMID 34447747, 2021). "But in cancer cells, they override the negative regulation of MST1/2, LATS1/2, MOB1 and SAV1, and result in inactivation of Hippo kinase cascade which leads to nuclear translocation of YAP and TAZ and the expression of downstream targets." (PMID 31941533, 2020). "Studies have reported that the expression levels of LATS1 and LATS2 proteins in malignant tumor tissues such as ovarian tumors and non-small-cell lung carcinoma are significantly lower than those in normal tissues." (PMID 32423384, 2020).
cancer (continued). "The results indicate that this scaffolding function of LATS1 plays a critical role in the regulation of autophagy and in therapy response of HCC cells and potentially other cancer type cells." (PMID 31848340, 2019). "It remains thus to be tested if the ambiguous findings related to the involvement of LATS1/LATS2 and other Hippo pathway components in the control of epidermal homeostasis and cancer development reflect such cell-intrinsic differences between mice and humans." (PMID 31058846, 2019). "Previous studies indicate that Lats1 can prevent cells from developing EMT and preventing cancer cells from metastasis." (PMID 31419991, 2019). "Mutations and altered expression of its core components (MST1/2, LATS1/2, YAP and TAZ) promote the migration, invasion, malignancy of cancer cells." (PMID 30961610, 2019). "LATS1/2 protein expression was similar for FIGO stage I + II and stage III + IV in borderline tumors and carcinomas and was also similar in grade 1 compared to grade 2 and grade 3 carcinomas." (PMID 31586262, 2019). "Our analysis identified genomic alterations in members of the canonical Hippo pathway, including LATS1 and NF2 in some cancers, whose potential role in YAP activation warrants further investigation in each individual cancer type." (PMID 29985391, 2018). "Several authors have noted promoter hypermethylation of MST1, MST2, LATS1, and LATS2 in various cancers." (PMID 30167083, 2018). "In cancer tissues, cases with high TNFAIP8 protein expression tended to show strong YAP nuclear staining and low p-LATS1." (PMID 28152516, 2017). "LATS1/YAP pathway is one major conserved mechanism governing cell contact inhibition, organ size control and cancer development." (PMID 25712415, 2015). "To date, the best characterised LATS1/2 function is the regulation of YAP/TAZ by phosphorylation, thereby playing a crucial role in mammalian cancer and stem cell biology." (PMID 23985307, 2013). "BPS altered DNA methylation patterns in the promoter regions of cancer-related genes and in another cell line (TNBC), triggering cell migration via activation of the Hippo-YAP pathway through GPER/PKC-mediated inhibition of LATS1/2." (PMID 41440754, 2025). "Cancer cell contractility is enhanced by ECM interaction, transmitting signals to the F-actin cytoskeleton and activating YAP/TAZ through either Hippo pathway-dependent or independent LATS1/2 phosphorylation." (PMID 39421027, 2024). "Deregulation of the Hippo pathway is one event contributing to cancer development and leading to a kinase cascade in which macrophage stimulating 1/2 kinases (MST1/2) phosphorylate large tumor suppressor kinase 1/2 (LATS1/2) and Salvador family WW domain containing protein 1 (SAV1)." (PMID 38388496, 2024). "Deletion of rodent Lats1/2 completely abolishes phosphorylation of Yap at Ser112 (homologous to human YAP Ser127) and maintains high YAP activity, which is essential for transforming the properties of YAP-dependent cancers." (PMID 38245531, 2024). "Since it is well known that the Hippo pathway is involved in cancer development, we predicted that METTL3 could mediate m6A modification of LATS1 and further affect the Hippo pathway." (PMID 36609396, 2023). "Notably, both integrins and cell-cell adhesion receptors can modulate upstream components in the Hippo pathway, such as NF2 and LATS1/2, leading to YAP activation in cancer cells." (PMID 38125873, 2023). "The lower expression of LATS1 and NCOR1 in basal-like cancers suggests that luminal tumors with diminished levels of either protein might be more susceptible to adopting basal-like attributes." (PMID 36443319, 2022). "Furthermore, SIRPγhi cancer cells displayed decreased p-MST1, p-LATS1, and p-YAP, and enhanced SOX2 expression compared with SIRPγlo/– cells." (PMID 35229723, 2022). "OTUB2 promoted cancer stemness and metastasis by deubiquitinating and stabilizing Yap/Taz in a manner independent of Lats1/2." (PMID 33869224, 2021).
cancer (continued). "Based on these two studies, we hypothesized that in cancer cells, overexpressed SHANK2 interacts with and sequesters ARHGRF7 away from LATS1, which then leads to reduced LATS1 activity and enhanced cell growth." (PMID 32661924, 2021). "On the other hand, binding of MK5 (also called MAPKAPK5 or PRAK) to Yap stabilizes Yap independent of Lats1/2, which is required for Yap-driven cancer progression." (PMID 33869224, 2021). "Since HERC4 and LATS1 genes are ubiquitously expressed, our findings suggest that HERC4 could have broad oncogenic activity in various human cancers." (PMID 30710319, 2019). "In cancer cells, human CRL4DCAF1 also binds to LATS1/2 and inhibits the proteins in the nucleus." (PMID 31170139, 2019). "However, methylation-mediated epigenetic mechanisms contribute to downregulation of LATS1/2, MST1/2, and its regulator RASSF1 in some cancer types." (PMID 31100975, 2019). "Recent studies have suggested that LATS1/2 and YAP, as the key components of the Hippo pathway, may be closely related to the response of cancer cells to chemo-therapeutic drugs such as cisplatin, Taxol and sorafenib." (PMID 30999669, 2019). "Other core components of Hippo pathway such as LATS1/2 also are critical for cancer therapy as negative effectors." (PMID 30961610, 2019). "The metabolic rewiring of cancer cells modulates the activity of the energy stress sensor AMP‐activated kinase (AMPK), which in turn controls YAP/TAZ signaling directly (by direct phosphorylation of YAP) or indirectly (by activating LATS1/2 or AMOTL2)." (PMID 31633874, 2019). "Recent studies have reported that mutations in the Hippo signaling components SAV1, MST1/2 and Lats1/2 are not evident in human cancer." (PMID 30961610, 2019). "In our IHC study the presence of LATS1 was observed only within the cytoplasm of normal and cancer cells, although in 40% of patients no or weak immunoreactivity was found in ccRCC cells." (PMID 29850494, 2018). "Therefore, we decided to assess the immunoreactivity of LATS1 and YAP1 proteins within the cancer and normal kidney tissue of patients with ccRCC." (PMID 29850494, 2018). "Meanwhile, by interacting with miRNAs, circRNAs also have the potential of impacting a variety of signaling pathways in cancers, such as vascular endothelial growth factor A (VEGFA) signaling pathway, large tumor suppressor kinase 1 (LATS1), Src family tyrosine kinases (SFKs) and so on." (PMID 29416705, 2018). "As the LATS1, YAP1, ∆Np63α cascade is a potent driver of cancer stem cell survival, we decided to determine whether SFN can suppress activity in this cascade as a mechanism to suppress ECS cell survival." (PMID 29088716, 2017). "Collectively, our findings show that MG relieves LATS1 control on YAP nuclear localization through a mechanism identifying for the first time MG-mediated post-translational glycation and inactivation of Hsp90 in cancer cells." (PMID 27759563, 2016). "ITCH involved in cancer progression mainly depends on its ability to regulate protein stability and the target proteins including p63, p73, Notch1, Dvl2, RASSF5, and LATS1." (PMID 27642589, 2016). "Hypoxia inhibited the LATS1 phosphorylation, which triggered the nuclear translocation of YAP and the subsequent activation of its target genes, contributing to the decreased anti-cancer activities of SN38 in hypoxic HCC cells." (PMID 26771844, 2016). "Taken together, LATS1/2 are central players in the regulation of YAP/TAZ functions in cancer and stem cell biology, although LATS1/2 also play significant roles in non-canonical Hippo signalling and even Hippo independent pathways." (PMID 23985307, 2013).
cancer (continued). "Whatever the case might be in cancer and stem cells, in mostly normal human cell lines (in particular HEK293 and MCF10A cells) LATS1/2 function downstream of G-protein-coupled receptors (GPCRs) as central controllers of YAP/TAZ activities." (PMID 23985307, 2013). "This discrepancy suggests that the role of LATS1 may not be universally consistent and could vary depending on the cancer type and context." (PMID 40699764, 2025). "ITCH is considered to have an important role in cancer development because of its capacity to control the ubiquitination and degradation of several proto-oncogenic proteins such as c-Jun, Cbl-b, and c-FLIP and tumor suppressor proteins, such as p63, p73, and LATS1." (PMID 38597989, 2024). "miR-21 is not only upregulated in cRCC but is also involved in cancer progression (proliferation, migration, invasion, epithelial mesenchymal transition) and the cancer stem cell phenotype by targeting tumor suppressor genes such as PTEN, PDCD4, TIMP3 or LATS1." (PMID 36359921, 2022). "WWP1 contains two WW domains that have been shown to recruit and modulate the activity of cancer related proteins like Runt-related transcription factor 2 (RUNX2), RING finger protein 11 (RNF11) and large tumor suppressor kinase 1 (LATS1) via their proline-rich (PY) motifs." (PMID 33869064, 2021). "Interestingly, while genetic ablation of MST1/2 in liver and intestine promotes tumorigenesis, deletion of LATS1/2 in liver or kidney does not result in the development of cancer." (PMID 31052239, 2019). "However, the intensity of LATS1 immunoreactivity varied between cancer cells since it was absent or weak in 22/54 (40.7%) and moderate to strong in 32/54 (59.3%) of ccRCC patients." (PMID 29850494, 2018). "However, how MST1/2, LATS1/2, SAV1, and MOB1 are simultaneously repressed to exhibit constitutively activated YAP/TAZ in cancer remains unclear." (PMID 26561204, 2015). "Following YAP mRNA downregulation, YAP protein levels decreased and in turn, the proliferation of cancer cells decreased; therefore, by reducing the inhibition of YAP, cancer cells decreased the expression of LATS1, demonstrating a novel negative feedback loop in the shYAP cells." (PMID 25625370, 2015). "To understand whether LATS1 stability is also regulated by other members of the NEDD4-like family of E3 ligases, we selected 4 ubiquitin ligases including NEDD4, WWP1, Smurf1 and Smurf2 that have been shown to be involved in the development of human cancers." (PMID 23573293, 2013). "Moreover, genetic analysis in human tumors did not provide a compelling case for the inactivation of LATS1 in human cancers." (PMID 19656388, 2009). "In addition, our results suggest that in addition to mRNA down-regulation by promoter hypermethylation, down-regulation of LATS1 at the protein levels through WWP1-mediated ubiquitination and degradation may be a novel mechanism by which LATS1 is down-regulated in various cancers." (PMID 23573293, 2013). "SIRPγ serves as a negative upstream regulator of the MST1/LATS1 axis to promote YAP activation and cancer organoid growth." (PMID 35229723, 2022). "Here, we report that PP2A Bβ interacts with LATS1 rather than MST1 or YAP in human placental tissues, PHTs, and HTR8/SVneo cells, which has been proposed in cancer research." (PMID 36250210, 2022). "We evaluated the expression of LATS1 and LATS2 proteins by immunohistochemistry among the non-cardia GC tissues and normal tissues adjacent to cancer in our pre-study." (PMID 32423384, 2020). "The results showed that the expression of LATS1 and LATS2 in non-cardia GC tissue was significantly lower than that in normal gastric tissue adjacent to cancer." (PMID 32423384, 2020). "Our study has used an unbiased bioinformatics analysis to identify a restrictive role of LATS1, but not LATS2, in Srf-induced autophagy in HCC and other cancer types and normal liver in vivo." (PMID 31848340, 2019).
cancer (continued). "We show in this study that LATS1 proteasomal degradation is favored in presence of MG thus bringing to light a new concept according to which MG stress could directly and/or indirectly participate to the control of tumor suppressor genes in cancer cells without affecting their transcriptional rate." (PMID 27759563, 2016). "To validate this, we examined the Hippo signaling in DSF-treated GES-1 and HGC-27 cells and found that DSF dose-dependently promoted the phosphorylation of LATS1, MOB1, and YAP in HGC27 cells but not GES-1 cells, results indicative of selectively reactivating Hippo signaling in cancer." (PMID 38657866, 2024). "Supporting this idea, it was shown that, unlike MOB1 or MOB2, MOB3 inhibits LATS1/2 signaling within the Hippo pathway and allows for continued proliferation of cells even after OIS, potentially contributing to cancer progression." (PMID 38803357, 2024).
infection (10 papers, 2009 to 2026). The state of being infected such as from the introduction of a foreign agent such as serum, vaccine, antigenic substance or organism. "Interestingly, the predominantly upregulated LATS1 phosphosite differed between the variants, with S613 being phosphorylated upon infection with Alpha, Beta, and Delta variants, and S464 upon Omicron BA.1 or BA.5 variant infection." (PMID 39653747, 2024). "During SARS-CoV-2 infection, activation of the Hippo pathway contributes to the host's antiviral response, and inhibition of upstream kinases MST1/2 and LATS1 enhances viral replication, indicating its protective role against infection." (PMID 40919176, 2025). "We induced luminal-specific LATS1/2 deletion in this system using two methods: (i) infection of Lats1/2f/f organoids with Ad-K8-nlsCre and (ii) 4-hydroxytamoxifen treatment of organoids grown from mammary cells isolated from Lats1/2f/f; K8CreERT2 mice." (PMID 36443313, 2022). "EMT marker (see in main text) expressions were measured in MDA-MB-231 cells with STARD13- or its ceRNAs-3′UTR overexpression plus LATS1 or LATS2 or LATS1/2 knockdown by lentiviral infection." (PMID 29848346, 2018). "LATS1/2 was knocked down in MDA-MB-231 cells with STARD13-correlated ceRNAs-3′UTR overexpressing by lentivirus shRNAs infection." (PMID 29848346, 2018). "Therefore, to explore the role of the immediate target of MST1/2 i.e. LATS1 in inducing the expression of chemokines, kinase dead form of LATS1/2 was over expressed in macrophages followed by infection with Mtb." (PMID 27883091, 2016). "Similarly, Lats1 expression was increased in the MCF10A human mammary epithelial cell line following infection with a retroviral vector expressing p75." (PMID 19656388, 2009). "Compared to the control group, the infection of HCMV significantly reduced the mRNA expression of Mst1, Mst2, SAV, Lats1, Lats2, Mob1, YAP1, TAZ, TEAD1-4 genes and YAP protein expression in the Hippo-YAP pathway." (PMID 34717661, 2021). "Recent studies show that upstream Hippo kinases such as MST1/2 and LATS1/2 often support antiviral responses, whereas YAP and TAZ can suppress innate immune signalling and may be exploited by viruses to promote infection." (PMID 42275403, 2026). "This is further supported by the observation LATS1/2 activities are not altered in the context of infection." (PMID 35503798, 2022). "Interestingly, blockade of LATS1/2 function did not affect the expression of any of the infection-induced chemokines." (PMID 27883091, 2016). "Interestingly, in cell lines that are not defective for CUX1, Lats1 expression was also stimulated following the infection of cells with a retrovirus expressing p110 or p75 CUX1." (PMID 19656388, 2009).
inflammation (2 papers, 2024 to 2025). Aberrant reaction of the microcirculation characterized by movement of fluid and leukocytes from the blood into extravascular tissues. "Collectively, our study suggests that ZLD1039 is a novel therapeutic agent for renal inflammation and fibrosis, with its specific molecular mechanism involving the up-regulation of LATS1 expression and the consequent inhibition of YAP activation." (PMID 40478495, 2025).
adenocarcinoma (1 paper, 2019). A common cancer characterized by the presence of malignant glandular cells. "Additionally, PIN lesions progress to PCa adenocarcinoma when combined with LATS1 loss in the Par3/LATS1 knockout (KO) murine model." (PMID 31018586, 2019).